IL6 (interleukin 6)
Diseases named in the same sentence as IL6 in open-access papers (continued):
Sharing a sentence is not in itself a finding about the gene and the disease.
Hyperglycemia (continued). "However, it remains unknown whether the dynamic changes of circulating TNF-α, IL-6 and nitrotyrosine induced by postchallenge hyperglycemia might be associated with CAD in patients without previously recognized T2DM." (PMID 22397368, 2012). "The major findings in this study were as follows: firstly, postchallenge hyperglycemia can rapidly elicit circulating TNF-α, IL-6 and nitrotyrosine levels after 75 g-OGTT in all patients regardless of glucose tolerance status or the presence or absence of CAD." (PMID 22397368, 2012). "Hyperglycemia spike had been shown to acutely increase the levels of circulating proinflammatory cytokines, including tumor necrosis factor-alpha (TNF-α) and interleukin-6 (IL-6), in subjects with IGT and these responses are attenuated by antioxidant." (PMID 22397368, 2012). "Experimental studies have shown that hyperglycemia stimulates the release of the inflammatory cytokines tumor necrosis factor-alpha (TNF-α) and interleukin-6 (IL-6) from various cells such as monocytes." (PMID 21663637, 2011). "In summary, our study shows that controlling post-meal hyperglycaemia with prandial + basal insulin attenuates the meal-induced increases in hsCRP, TNF-α and interleukin-6 compared with basal insulin once daily, both plus metformin." (PMID 21517955, 2011). "In a porcine model, stress hyperglycemia led to a significantly enhanced inflammation as shown by elevated TNF-α and IL-6 levels." (PMID 18710523, 2008). "The induction of acute hyperglycaemia in healthy humans elevated circulating levels of TNF-α and IL-6, although these elevations were very modest, especially when compared with cytokine increases observed during inflammatory reactions." (PMID 18290856, 2008). "Taken together, these findings suggest that IL-6 elevation is not simply a reflection of hyperglycemia but rather reflects the interaction between poor metabolic control and underlying autoimmunity in T1D." (PMID 41010714, 2025). "Hyperglycemia triggers immune cells to release inflammatory mediators (including TNF-α, IL-1β, IL-6, NF-κB, TGF-β, and adhesion molecules), which further contribute to β-cell dysfunction, insulin resistance, and progression of complications such as vascular damage, neuropathy, and CVD cell loss." (PMID 40299501, 2025). "Chronic and inadequately treated hyperglycemia in patients diagnosed with DM can activate inflammatory responses through citokine production (TNF-α, NFkB, IL-1, IL-6, etc.)from various types of cells (such as macrophages, lymphocytes, granulocytes, fibroblasts, mast and endothelial cells)." (PMID 40299501, 2025). "Interestingly, hyperglycemia and/or aging induces ROS from NOX1 that forms a positive feedback loop with IL6 in both in human and murine endothelial cells." (PMID 40023978, 2025). "The present findings showed that hyperglycemia promoted the pro-inflammatory phenotype in macrophages, which was characterized by increased expressions of marker pro-inflammatory mediators, including TNF-α, IL-6, IL-1β, and iNOS." (PMID 40001441, 2025). "Systemically, the intervention effectively alleviated hyperglycemia, HOMA-IR, hyperlipidemia, and serum MDA levels, reduced NAS and liver TNF-α levels, while having no appreciable effect on adiposity, serum insulin levels, or liver IL-6, TG, and TC levels." (PMID 40427484, 2025). "Trends in IL-1 and IL-6 can be challenging to interpret, with occasional cases of unexplained hyperglycemia without significant inflammatory response." (PMID 40134446, 2025). "Together, these findings demonstrate that hyperglycemia dose-dependently suppresses NK cell cytotoxicity while amplifying IL-6 production, independent of subset frequency alterations." (PMID 40471558, 2025). "Postprandial hyperglycemia, more than continuous hyperglycemia, triggers a transient increase in circulating proinflammatory cytokines, including tumor necrosis factor-α (TNF-α) and interleukin-6 (IL-6) through oxidative mechanism." (PMID 40671150, 2025).
Hyperglycemia (continued). "Hyperglycemia increases the production of glycation end products, reactive oxygen species, and proinflammatory cytokines (such as Tumor Necrosis Factor Alpha (TNF-α) and interleukin-6 (IL-6)) in plasma." (PMID 41578817, 2025). "Persistent hyperglycemia activates nuclear factor kappa-light-chain-enhancer of activated B cells (NF-κB), inducing the production of pro-inflammatory cytokines such as tumor necrosis factor-alpha (TNF-α) and interleukin-6 (IL-6)." (PMID 39872596, 2024). "Hyperglycemia in DM leads to the glycation of various proteins, triggering an inflammatory milieu at the cellular and tissue levels, with increased cytokines levels such as tumour necrosis factor-alpha (TNF-α), interleukin-6, and C-reactive protein." (PMID 39553031, 2024). "Consistent with our in vitro model of hyperglycemia, CD34+ cells from CAD-T2DM patients displayed, a significant upregulation of CDKi p21 and p27 genes as well as upregulation of proinflammatory genes (IL6 and TNFα), and their transcription factor NFkB-p65." (PMID 38553774, 2024). "Hyperglycemia and oxidative stress induce NF-κB activation, which translocates to the nucleus and initiates the transcription of pro-inflammatory and pro-fibrotic genes such as TNF-α, IL-6, and MCP-1." (PMID 39795078, 2024). "When PTEN undergoes polyubiquitination at lysine 80 through MEX3C-mediated K27 linkage, it exhibits a pro-inflammatory effect by promoting the secretion of interleukin-6 (IL-6) and transforming growth factor-beta 1 (TGF-β), thereby exacerbating hyperglycemia-induced EMT." (PMID 39165377, 2024). "Furthermore, chronic exposure to hyperglycemia can produce inflammatory factors such as tumor necrosis factor-alpha (TNF-α) and interleukin-6 (IL-6)." (PMID 38778429, 2024). "Secondly, hyperglycemia promotes the chronic release of inflammatory mediators such as tumor necrosis factor-alpha (TNF-α) and interleukin-6 (IL-6), creating a pro-inflammatory environment that leads to the accumulation of collagen and extracellular matrix, ultimately resulting in fibrosis." (PMID 39407755, 2024). "Hyperglycemia triggers podocytes, mesangial cells, and tubule cells to release IL-6, contributing to systemic and localized subclinical inflammation, and the use of SGLT-2i has been demonstrated to reduce IL-6 levels." (PMID 39201363, 2024). "Other pro-inflammatory mediators underpinning DR (e.g., interleukins (IL)-6 and IL-8) were not significantly affected by exacerbated mitochondrial fusion under hyperglycaemia." (PMID 38321058, 2024). "In BMDMs, STZ-induced hyperglycemia did not alter the IL-6 production induced by LPS or poly(I: C).Similarly, the level of LPS-induced IL-6 production in peritoneal macrophages was not affected by STZ-induced hyperglycemia." (PMID 38802820, 2024). "We observed a significantly lower lymphocyte count, higher NLR, and higher IL-6 and CRP levels in patients with mild and intermittent hyperglycaemia, presuming that the inflammatory response is more pronounced in patients with increased glucose levels at admission." (PMID 38255162, 2023). "All immunological biomarkers (ferritin, LDH, CRP, procalcitonin, IL-6, and CRP/ALB), coagulation biomarkers (aPTT, D-dimer, fibrinogen, PT, and INR), and hyperglycemia biomarkers (random glucose and HbA1c) were significantly higher in the severe patients compared to the other severity groups." (PMID 37448393, 2023). "Additionally, hyperglycemia can decrease trimethylation of H3K9 at the promoter region of IL-6 in human monocytes, resulting in increased IL-6 expression." (PMID 36687556, 2023). "In addition, hyperglycemia promoted the release of proinflammatory factors such as tumor necrosis factor-α(TNF-α) and interleukin-6 (IL-6) in vitro." (PMID 37008926, 2023). "In addition, stress-induced hyperglycemia can also trigger an inflammatory response, such as increasing the production of inflammatory cytokines (such as TNF-α, IL-1β, and IL-6), which further exacerbate lung tissue inflammation." (PMID 37658378, 2023).
Hyperglycemia (continued). "Human experimental studies have shown that inducing acute hyperglycaemia in healthy individuals increases IL-6 levels with or without LPS stimulation." (PMID 38202252, 2023). "Pio also has broad anti-inflammatory activity, exemplified by its ability to significantly reduce interleukin-6 (IL-6) and tumor necrosis factor α (TNFα) in insulin resistant individuals without manifest hyperglycemia matched for age, gender, and adiposity." (PMID 35743273, 2022). "The occurrence of stress hyperglycemia involves activation of the hypothalamic-pituitary axis and sympatho-adrenal system and increases the release of epinephrine, norepinephrine, and pro-inflammatory cytokines (TNF-α, IL-1, and IL-6)." (PMID 35645975, 2022). "Moreover, in the pathological state of hyperglycemia and hemodynamic disorder, a large number of renal macrophages are infiltrated, and multiple inflammatory cytokines such as IL-1β, TNF-α, and IL-6 are released." (PMID 35355720, 2022). "Hyperglycemia-induced polymorphonuclear (PMN) dysfunction has been related (in patients with and without DM) to a significantly reduced chemotaxis and with increased complications in these patients due to increased secretion of IL-1, IL-6 and TNF-α." (PMID 35096863, 2021). "Overall rate of change in slope 88.54 (95% CI:-143.39–33.68) points was found more in hyperglycemia than normoglycemia group (p = 0.002) for IL-6 values, whereas there was no statistical significant change in slopes of age, gender and their interaction." (PMID 34117510, 2021). "Previous studies have demonstrated that hyperglycemia activates the innate immune response mediated by TLR2, TLR4, and the NLRP3 inflammasome, inducing the production of various proinflammatory cytokines, including IL-1β, IL18, IL-6, and TNFα." (PMID 34356130, 2021). "Therefore, we aimed to analyze the effects of JMJD1A on inflammatory proteins including IL-6, IL-8, ICAM-1, and MCP-1 under hyperglycemia and hypoxic stimulation of HUVECs." (PMID 34479471, 2021). "Hyperglycaemia‐induced oxidative stress promotes inflammation through increased endothelial cell damage, microvascular permeability and increased release of pro‐inflammatory cytokines, including TNF‐α, interlukin‐1β (IL‐1β) and interlukin‐6 (IL‐6)." (PMID 33108705, 2020). "In non-diabetic patients, induced hyperglycemia led to an amplification of interleukin-6 (IL-6) and other pro-inflammatory markers." (PMID 32430795, 2020). "In order to obtain insight into the inflammatory processes induced by hyperglycemia, we examined the expression levels of four proinflammatory cytokines, namely, TNF-α, IL-6, IL-8, and IL-1α, under hyperglycemic conditions with or without anthocyanin-rich sour cherry extract." (PMID 33147748, 2020). "Hesperidin reduced hyperglycaemia, decreased malondialdehyde (MDA) and IL-6 levels, and enhanced the brain-derived neurotrophic factor (BDNF) and monoamines in the brain, thereby enabling it to be effective in treating and managing neurogenesis in diabetic rats." (PMID 32977511, 2020). "Despite similar levels of hyperglycemia and similar daily insulin doses, only in progressors was activation of the NF-κB pathway observed, as indicated by the overexpression of TLR4, nuclear p65 and IL-6." (PMID 32116790, 2020). "Hyperglycemia increased ROS, TNF-α and IL-6, and reduced miR-24 and miR-126 levels in plasma." (PMID 33680027, 2020). "Moreover, inflammatory markers and mediators such as c-reactive protein (CRP), interleukin-6 (IL-6) and TNF-α are present in systemic inflammation induced by hyperglycemia." (PMID 32932898, 2020). "Hyperglycemia-induced ROS and AGEs production may stimulate the secretion of proinflammatory cytokines, such as TNF-α and IL-6, in renal tissues." (PMID 33447179, 2020).
Hyperglycemia (continued). "For example, Optimal COVID-19 infection management with TCZ is not achieved during hyperglycaemia in both diabetic and non-diabetic patients that TCZ administration neither decreases IL-6 levels nor attenuates risk of severe outcomes." (PMID 33195318, 2020). "We observed that both hyperglycemia and glucose fluctuations induced polarization transitions to M1 phenotype in microglia, leading to increased expression of pro-inflammatory factors including TNF-α and IL-6." (PMID 31695681, 2019). "However, compared to changes in controls, participants in the Mediterranean diet arm had no significant changes in any of the inflammatory biomarkers or adipokines (IL-6, IL-8, CRP, and adiponectin), markers of hyperglycemia (FPG and insulin), or FMD." (PMID 30271610, 2018). "While IL-6 alone, at least at the dosage used, was not sufficient to protect against olanzapine-induced hyperglycemia this does not discount a potential role for IL-6 in mediating the protective effects of exhaustive exercise." (PMID 29335597, 2018). "As with our initial experiment IL-6 treatment did not attenuate olanzapine-induced hyperglycemia (saline + olanzapine 1381 ± 94 glucose AUC, IL-6 + olanzapine 1403 ± 120 glucose AUC, n = 8/group)." (PMID 29335597, 2018). "The up-regulation of several hormones (glucagon, growth hormone, catecholamines, and glucocorticoids), inflammatory mediators (interleukin (IL)-1, IL-6, Intercelluar Adhesion Molecule (ICAM-1), and tumor necrosis factor (TNF)-alpha) accompanies the development of hyperglycemia." (PMID 27110221, 2016). "In humans, data suggest that plasma IL‐6 levels are increased in critically ill subjects admitted with hyperglycemia but these levels were measured randomly and not during controlled, provocative metabolic testing." (PMID 27042306, 2016). "Moreover, hyperglycemia and metformin resulted in an increase of the mRNA levels of HGF (1.7-fold, p = 0.001), and IL-6 (2.8-fold, p = 0.01) although this increase remained below normal level observed at euglycemia." (PMID 26861446, 2016). "In our study, an acute increase in PG could increase the plasma levels of IL-6, TNF-α and ICAM-1 and their expression by vascular endothelial cells, and greater inductions were observed following exposure to fluctuant hyperglycemia." (PMID 27496150, 2016). "In addition, hyperglycemia, by itself, is known to augment the production of inflammatory cytokines such as tumor necrosis factor-α (TNF-α) and interlukin-6 (IL-6)." (PMID 26207186, 2015). "The Mediterranean diet also reduced the negative effects of acute hyperglycemia, induced by a hyperglycemic clamp, on endothelial function, nitrotyrosine, 8-iso-PGF2a, IL-6 and ICAM-1 levels." (PMID 25407792, 2014). "However, after 2 h of recovering in hyperglycemia, FMD decreased, and sICAM-1, 8-iso-PGF2a, nitrotyrosine and IL-6 were increased even more significantly compared to basal as well as to the recovery in normoglycemia." (PMID 23806096, 2013). "When the recovery in hyperglycemia was accompanied by the simultaneous infusion of GLP-1, all these phenomena were significantly attenuated: FMD decreased less, while sICAM-1, 8-iso-PGF2a, nitrotyrosine and IL-6 were less increased." (PMID 23806096, 2013). "Even acute hyperglycemia in non-diabetics has been reported to elevate plasma IL6 and TNFα concentrations." (PMID 23028447, 2012). "Luteolin ameliorated hyperglycemia and improved hypoinsulinemia, β-cell dysfunction, and renal impairment in HFD-STZ-induced diabetic rats by attenuating inflammation and dysregulated cytokine secretion through modulation of PPAR-γ, TNF-α, IL-6, and NF-kB expression and down-regulation of SREBP-1c." (PMID 40076380, 2025). "Besides, Hyperglycemia promotes the secretion of pro-inflammatory cytokines including C-reactive protein (CRP), interleukin-6 (IL-6), and tumor necrosis factor-alpha (TNF-α), all of which have been shown to contribute to DKD progression and cardiovascular disease development." (PMID 40747306, 2025).
Hyperglycemia (continued). "First, hyperglycemia activates microglial cells via the AGE-RAGE axis, leading to an increase in blood–brain barrier (BBB) permeability, which subsequently promotes the infiltration of pro-inflammatory cytokines such as IL-6 and TNF-α into the brain parenchyma." (PMID 40242624, 2025). "In conditions characterized by high metabolic stress and hyperglycemia such as DKA, investigating the effects of inflammatory markers such as IL-6 on the duration of ICU stay and the general recovery process may contribute to the development of strategies to improve clinical outcomes." (PMID 40005437, 2025). "It triggers systemic changes like hyperglycemia and hyperinsulinemia and increases levels of adipose tissue-derived estrogens, adipokines, and inflammatory mediators (e.g., prostaglandin E2 [PGE2], tumor necrosis factor [TNF], and IL-6), stimulating cancer growth." (PMID 40040878, 2025). "In line with our in vitro model of hyperglycemia, at the end of differentiation, CAD-T2DM-derived monocytes still showed, as their precursors, high expression levels of CDKi p21 and p27 genes, and release, after LPS stimulation, of proinflammatory IL6 and TNFα cytokines." (PMID 38553774, 2024). "In addition, hyperglycemia induces certain inflammatory factors [tumor necrosis factor-α (TNF-α), interleukin-6 (IL-6), C-reactive protein (CRP), etc.] and inflammatory reactions, all of which cause varying degrees of damage to cardiomyocytes, blood vessels, and even the heart." (PMID 37448666, 2023). "Therefore, and contrary to what we expected, a double inflammatory stimulus by severe hyperglycemia and S. agalactiae infection resulted in a weaker inflammatory profile, despite each one of these insults alone led to increased TNF-α and IL-6 production in comparison to normoglycemia." (PMID 36982317, 2023). "Notably, pretreatment with insulin or metformin did not modify the decreased secretion of TNF-α and IL-6 observed under hyperglycemia." (PMID 36982317, 2023). "Hyperglycemia is closely related to the excess generation of reactive oxygen species (ROS) and oxidative stress which can up-regulate the levels of inflammatory factors including tumor necrosis factor-alpha (TNF-α), interleukin-6 (IL-6) and reduces the level of interleukin 10 (IL-10)." (PMID 37396948, 2023). "Hyperglycemia leads to pro-oxidative substance generation, results in oxidative stress and PARP activation, affects nuclear factor-κB activation, and subsequently leads to the secretion of inflammatory substances, including COX-2, IL-1β, and IL-6 by Schwann cells." (PMID 37960130, 2023). "Also, the comparison of IL-6 between subjects with and without hyperglycemia showed a considerable trend towards significance (p=0.069) with hyperglycemic patients exhibiting higher levels of the inflammatory cytokine." (PMID 37529617, 2023). "Hyperglycemia leading to the activation of alternative pathways of glucose metabolism (Polyol, PARP, protein kinase C, hedgehog and more) leads to the formation of AGEs, ROS, lipooxygenase pathways (LOX) and an elevation of proinflammatory cytokines (IL-6 and TNFɑ)." (PMID 37483613, 2023). "Consequently, down-stream biomarkers of inflammation that may have responded to hyperglycaemia and hyperglycaemia-induced oxidative stress, namely CRP and IL-6, were unchanged." (PMID 38231672, 2023). "However, in diabetic animals, hyperglycemia and ischemia lead to a significant increase in the expression and activation of TLR4, thereby promoting inflammation through downstream cytokines (such as IL-6)." (PMID 35463063, 2022). "The possible explanation might be persistent hyperglycemia has a direct relationship with the non-enzymatic glycation of various proteins and the increased expression of pro-inflammatory cytokines such as IL-6, and TNF- α in blood circulation." (PMID 35895700, 2022).